SMC3 (structural maintenance of chromosomes 3)
Diseases named in the same sentence as SMC3 in open-access papers (continued):
Sharing a sentence is not in itself a finding about the gene and the disease.
sarcoma (1 paper, 2020). A usually aggressive malignant neoplasm of the soft tissue or bone. "We investigated this in the ONCOMINE and GEPIA datasets, and found that the expression of SMC3 was higher in human sarcoma than in normal tissues." (PMID 33460400, 2020). "Therefore, we speculated that SMC3 was also associated with the progression of sarcoma." (PMID 33460400, 2020). "The results of CCLE dataset analysis also showed that SMC3 was highly expressed in human sarcoma cell lines." (PMID 33460400, 2020). "GEPIA was used to investigate the prognostic ability of SMC1, SMC2, SMC3, SMC4, SMC5 and SMC6 expression in sarcoma." (PMID 33460400, 2020). "It was confirmed that the expression levels of SMC1A, SMC2, SMC3, SMC4, SMC5 and SMC6 in sarcoma were higher than in normal tissues." (PMID 33460400, 2020). "According to the Cancer Cell Line Encyclopedia (CCLE), SMC1A, SMC2, SMC3, SMC4, SMC5 and SMC6 are also highly expressed in sarcoma cell lines." (PMID 33460400, 2020). "We concluded that SMC1A, SMC2, SMC3, SMC4, SMC5 and SMC6 were all highly expressed in sarcoma cell lines." (PMID 33460400, 2020). "Our results also suggest that SMC1A and SMC2 are potential therapeutic targets for sarcoma, while levels of transcripts of SMC3, SMC4, SMC5 and SMC6 are potential prognostic markers to improve the survival rate and prognostic accuracy of sarcoma." (PMID 33460400, 2020). "We found that increased expression of SMC1A, SMC2, SMC3, SMC4, SMC5 and SMC6 might play a significant role in sarcoma tumorigenesis." (PMID 33460400, 2020). "However, only the overexpression of SMC1A and SMC2 was related to the OS of sarcoma patients, whereas SMC3, SMC4, SMC5 and SMC6 had no significant impact on prognosis." (PMID 33460400, 2020). "In contrast, SMC3, SMC4, SMC5, and SMC6 expression had no significant impact on OS or DFS in sarcoma." (PMID 33460400, 2020).
Stillbirth (1 paper, 2025). Death of the fetus in utero after at least 22 weeks of gestation. "A study on exome sequencing found that missense mutations of COL2A1, PEIZO1, and HNF1B were associated with stillbirth, and ultra-rare variants in PTPN11, SMC3, and FBN2 were known to cause stillbirth." (PMID 39906474, 2025).
synovial sarcoma (1 paper, 2020). "This revealed that SMC1A, SMC2, SMC3, SMC4, SMC5 and SMC6 proteins were all more highly expressed in the synovial sarcoma tissues than in corresponding normal tissues." (PMID 33460400, 2020).
virus infection (1 paper, 2023). "Furthermore, the downregulation of Smc3 in influenza A virus-infected lung epithelial cells and in damaged axons was observed, suggesting that a decrease in SMC3 is a part of the response to virus infection and other cellular stress." (PMID 37505703, 2023).
cancer (26 papers, 2010 to 2026). A tumor composed of atypical neoplastic, often pleomorphic cells that invade other tissues. "The effects of limited amounts of Mcd1and Smc3 indicate that small changes in cohesin levels may increase the risk of genome instability, which may lead to genetic diseases and cancer." (PMID 20617204, 2010). "The core complex subunits SMC1A, SMC3, STAG1/2, and RAD21 as well as its modulators, have been found to be recurrently mutated in human cancers." (PMID 35287703, 2022). "recently showed that cell cycle signaling was associated with high cancer stemness of EAC, such as E2F3, CHEK1, CDC20, SMC3, and TFDP1." (PMID 35785171, 2022). "A subsequent study expanded this initial proof-of-principle to include five additional genes, which are frequently mutated in cancer (CDC4, MRE11A, RNF20, SMC1A, and SMC3) that are also selectively killed following FEN1 inhibition." (PMID 24202319, 2013). "It is noteworthy that BRCA1 and SMC3 are present at the plasma membrane and basement membrane respectively and involved in the regulation of cell spreading and motility in cancer cells." (PMID 23717600, 2013). "Additionally, we found that the levels of SMC3 acetylation were impaired in cancer cells lines harboring STAG2 inactivation (H4 parental and TC-106 STAG2 knockout cells) relative to their STAG2 wildtype counterparts (H4 STAG2 knock-in and TC-106 parental cells)." (PMID 30975996, 2019). "In support of this model, elevated expression of almost every cohesin subunit (RAD21, SMC1A, SMC3, STAG1, PDS5, WAPL) and cohesin regulator (NIPBL, MAU2) appears to be oncogenic and present in a wide range of cancer cells." (PMID 41370327, 2025). "Studies found that SMC3 activates nuclear factor-κB (NF-κB) through autocrine tumor necrosis factor-α (TNF-α), which inhibits apoptosis in cancer cells." (PMID 34123852, 2021). "Taken together, these data suggest that BUB1, STAG2, SMC3, and THOC1 function in cell growth, proliferation, and tumorigenesis and thus play crucial roles in cancer development." (PMID 32518584, 2020). "In various types of cancers, numerous studies have now documented a link between EIF4A3, SMC3, ESPL1, CDC25B, CCNA2, or AURKA and their response to therapy." (PMID 32454908, 2020). "Last, SMC3 is reported as a nonhistone substrate of HDAC in cancer and has been shown to be involved in the restructuring of the chromatin architecture in SARS-CoV-2 infection." (PMID 40378209, 2025). "In cancer cells, cohesin binding through the genome is reinforced following ionizing radiation (IR), in a process that requires ATM and SMC3 phosphorylation, and SMC3 acetylation by ESCO1." (PMID 22988450, 2012). "Our previous work established that regions bound by BORIS alone in cancer cell lines were not occupied by cohesin subunits RAD21 and SMC3, indirectly suggesting that BORIS is not able to retain cohesin." (PMID 31937660, 2020). "In contrast, inactivation of the cohesin ring subunits SMC1A, SMC3, and RAD21 is not compatible with viability in both primary non-transformed human cells and human cancer cell lines." (PMID 30975996, 2019).
tumor (16 papers, 2006 to 2024). "Because aneuploidy is thought to contribute to malignant transformation and tumor progression, these data suggest a link between smc3 haploinsufficiency or loss-of-function and tumorigenesis." (PMID 17081288, 2006). "Although tumors derived from Smc3 haploinsufficient B cells display a Kmt2d loss of function-like transcriptional profile, we did not detect consistent downregulation of Kmt2d mRNA itself in tumor cells." (PMID 34621263, 2021). "Interestingly, we found that only 8 genes were mutated in at least one Bcl6 tumor, while 119 of them were mutated in at least one Smc3/Bcl6 tumor." (PMID 34621263, 2021). "Tumor suppressor genes Kmt2d and Dusp4 showed similar loss of interactivity of their promoters with putative H3K27Ac rich loci in Smc3/Bcl6 tumors." (PMID 34621263, 2021). "Evidence from previous studies suggests that the chromatid cohesion defects may underlie chromosome instability and tumour development, emphasizing the role of SMC3 and SMC1A as candidate drivers." (PMID 33319839, 2020). "SMC3 knockdown also reversed the tumor-promoting effects of RIT1 in vivo in mouse subcutaneous tumor experiments." (PMID 38017479, 2023). "Hi-C contact maps revealed little difference globally between Smc3/Bcl6 vs Bcl6 tumor interactivity profiles." (PMID 34621263, 2021). "Although Smc3/Bcl6 tumors showed higher variability in the total numbers of somatic mutations, these were not significantly different than tumor cells from the Bcl6 (Wilcoxon p=0.24)." (PMID 34621263, 2021). "Indeed further examination of chromatin compartment distribution in Smc3/Bcl6 vs Bcl6 and tumor cells showed very little difference between these genotypes." (PMID 34621263, 2021). "Acetylation protection of SMC3 by RIT1 during mitosis may partially rescue mitotic errors caused by the negative regulation of SAC by RIT1, thereby ensuring efficient division and proliferation of tumor cells to drive tumor progression." (PMID 38017479, 2023). "RIT1 protects and maintains the acetylation of SMC3 through its interaction with PDS5, thereby ensuring rapid mitotic progression in HCC cells and promoting tumor progression." (PMID 38017479, 2023). "SMC3 haploinsufficiency accelerates lymphomagenesis in mice with constitutive BCL6 expression and is considered a putative tumor suppressor for germinal center B cells." (PMID 36499305, 2022). "The identified potential tumor suppressor genes included DAG1, SLC39A8, TMEM173/STING1, RDX, TJP1, CTNNB1, and SMC3." (PMID 36499305, 2022). "We found that increased expression of SMC2, SMC3, and SMC4 might play a significant role in HCC, and could be useful as molecular markers to identify high-risk patients, Our results also provide insights for further research of SMC family members as potential tumor therapeutic target in HCC." (PMID 36281130, 2022). "This HDAC8-dependent mechanism is rather likely to happen in an SMC3 independent manner, as no changes of SMC3 acetylation levels were observed in tumor cells sensitized by HDAC8i treatment." (PMID 35016723, 2022). "SMC2, SMC3, and SMC4 are also related to tumor purity and immune infiltration levels of HCC." (PMID 36281130, 2022). "In addition, consistent with previous research results, we also found that SMC1A, SMC1B, SMC2, SMC3, SMC4, and SMC6 were overexpressed at the mRNA level in HCC when compared with non-tumor cells." (PMID 34527684, 2021). "HCH could reverse the pathological lung tissue into approximately normal, the protein expression of Ki-67, VEGF and SMC3 were all reduced, the ROS level was reduced andSOD level was increased, the levels of IL-1β, IL-8, IL-13 and TNF-α were all reduced, the weights of tumor were reduced." (PMID 39211045, 2024). "Furthermore, PCI-34051 treatment at concentrations showing tumor cell phenotype impairment (5–10 μΜ) did not result in a further increase of ac-SMC3 neither in basal growth conditions nor upon chemotherapy." (PMID 35016723, 2022).
tumor (continued). "To date, the literature supports the tumor suppressor functions of DAG1, SLC39A8, TMEM173/STING1, TJP1, CTNNB1, and SMC3, but not RDX." (PMID 36499305, 2022).
) malformation syndrome (2 papers, 2018 to 2022). "CdLS, an autosomal dominant (NIPBL, SMC3, and RAD21) or X-linked (SMC1 and HDAC8) malformation syndrome, represents the best characterized cohesinopathy." (PMID 36467423, 2022). "The best characterized cohesinopathy is CdLS, an autosomal dominant (NIPBL, SMC3, and RAD21) or X-linked (SMC1A and HDAC8) malformation syndrome." (PMID 36467423, 2022).
SMC3 also shares sentences with these, for which no sentence is quoted: genetic disorder (5 papers); leukemia (5); Intellectual disability (4); (CAID) syndrome (3); autism spectrum disorder (2); chronic myeloid leukemia (2); infection (2); lung adenocarcinoma (2); melanoma (2); myeloid leukemia (2); Warsaw breakage syndrome (2); brachydactyly (1); Clinodactyly (1); Coffin-Siris syndrome (1); developmental disabilities (1); diaphragmatic hernia (1); Down syndrome (1); endometriosis (1); Ewing sarcoma (1); familial restrictive cardiomyopathy-6 (1); growth deficiency (1); heart diseases (1); hemorrhage (1); hepatocellular carcinoma (1); Huntington disease (1); Kabuki syndrome (1); liposarcoma (1); lung disease (1); lymph node (1); Meckel-Gruber syndrome (1).
A further 17 diseases each share a sentence with SMC3 in 1 paper.